KRAS (KRas proto-oncogene, GTPase)
Diseases named in the same sentence as KRAS in open-access papers (continued):
Sharing a sentence is not in itself a finding about the gene and the disease.
myeloma (continued). "KRAS and NRAS exon 3 mutations were significantly associated with the myeloma cohort compared with non-myeloma plasma cell dyscrasias (odds ratio (OR) 9.87, 95% confidence interval (CI) 1.07–90.72, P=0.043 and OR 7.03, 95% CI 1.49–33.26, P=0.014)." (PMID 28234344, 2017). "We found an overlap of mutations in KRAS and NRAS genes activating mitogen-activated protein kinase signaling in 5/54 myeloma patients (9.3%), most likely in different tumor subclones because of different percentages of mutant reads." (PMID 28234344, 2017). "In this study, we identified mutations in three well-known oncogenes, KRAS, NRAS, and BRAF, in multiple myeloma patients." (PMID 27634910, 2016). "Mutation analysis of all myeloma patients including the six patients with AL amyloidosis revealed NRAS as the most commonly mutated gene (30%, 7/23), followed by KRAS (26%, 6/23) and BRAF (22%, 5/23)." (PMID 27634910, 2016). "We therefore tended to study the metabolic shift in myeloma cells with KRAS/NRAS/BRAF WT background in response to EGFR inhibition, which was expected to confer primary efficacy." (PMID 25894462, 2015). "In this study, our results suggested that both the myeloma cell lines, 8226 (KRAS G12A) and H929 (NRAS G13D), are sensitive to SHP2 inhibitors, the latter of which contradicts previous reports that RAS G13D–mutated cancer cells are resistant to SHP2 inhibition." (PMID 35462913, 2022). "The most frequent mutations involve KRAS and NRAS genes in multiple myeloma." (PMID 34017329, 2021). "Notably, 6 of the 23 myeloma patients showed multi-site and/or multi-gene mutations in NRAS, KRAS, or BRAF, indicating compound aberrations in the Mitogen activated protein kinase (MAPK) pathway." (PMID 27634910, 2016). "Interestingly, it has been shown that mutated forms of BRAF, NRAS, and KRAS can upregulate non-constitutive proteasome expression and reduce endoplasmic reticulum stress in multiple myeloma." (PMID 38774235, 2024). "For instance, the use of mut-KRAS patient-derived organoids and xenografts would represent an invaluable preclinical model to test novel proteasome inhibitors already in clinical trials for multiple myeloma, such as ONX 0914, carfilzomib, ixazomib and oprozomib." (PMID 34065438, 2021). "In multiple myeloma the mutational profile is mainly represented by translocations involving chromosome 14 and by single nucleotide mutations, frequently involving genes implicated in the mitogen activated protein kinase (MAPK) pathway, as KRAS, NRAS, and, less frequently, BRAF." (PMID 31709194, 2019). "In mature B cell neoplasms, commonly seen in adults, KRAS and RAS-MAPK pathway aberrations occur in a relevant fraction of patients, reaching high recurrence in some specific subtypes like multiple myeloma and hairy cell leukemia." (PMID 35158933, 2022). "We report here a hybrid-capture-based Liquid Biopsy Sequencing (LB-Seq) method used to sequence all protein-coding exons of KRAS, NRAS, BRAF, EGFR and PIK3CA in 64 cfDNA specimens from 53 myeloma patients to >20,000 × median coverage." (PMID 28492226, 2017). "Unlike other malignancies, mutations of KRAS and NRAS were found in approximately equal rates in myeloma." (PMID 27634910, 2016). "This may be due to either functional differences between KRAS and NRAS as oncogenic drivers or the different biology of myeloma compared to solid tumors." (PMID 26709701, 2015). "Recent clinical data in multiple myeloma patients presents an interesting case, where NRAS but not KRAS mutations were associated with lower response to single-agent bortezomib." (PMID 26709701, 2015).
Noonan syndrome (66 papers, 2010 to 2026). "An in-house database search for insertions comparable to the VMOS RAS variants revealed one in-frame insertion in KRAS in a case suspected for Noonan syndrome." (PMID 31160609, 2019). "Germline or somatic mutations of KRAS are implicated in several human diseases like the Noonan syndrome, cardio-facio-cutaneous (CFC) syndrome, and Costello syndrome, as well as in different types of solid and non-solid tumor." (PMID 30012129, 2018). "Pathogenic gain-of-function variants in RAF1—among other genes including PTPN11, SOS1, and KRAS—cause Noonan syndrome." (PMID 30597917, 2018). "Craniosynostosis is a rare but previously recognised complication of Noonan syndrome, being particularly associated with KRAS mutations." (PMID 27884935, 2017). "SOS1 and KRAS, but not SOS2, have been implicated in human rasopathies, including mutations in SOS1 and KRAS in Noonan syndrome and KRAS mutations in cardiofaciocutaneous syndrome." (PMID 23761422, 2013). "Here we report on a case of an infant with Noonan syndrome and rapidly progressive hypertrophic cardiomyopathy with lethal outcome, in whom we identified a novel mutation in the KRAS gene." (PMID 24382853, 2013). "While the Noonan syndrome associated KrasV14l exhibits attenuated biochemical activation compared to common cancer associated KRAS alleles, strong activation was shown for Ptpn11D61Y, which is frequently linked to juvenile myelomonocytic leukemia (JMML) in patients." (PMID 38910965, 2024). "Mutations in the following genes that cause Noonan syndrome have been identified: RAS family GTPase proteins (KRAS, NRAS, RIT1, and RRAS), RAS signal function modulators (PTPN11, SOS1, SOS2, CBL, RASA2, and SHOCS2), and downstream signal transducers (RAF1 and BRAF)." (PMID 38248880, 2023). "JMML has occasionally been described in KRAS mutated Noonan syndrome." (PMID 35819517, 2022). "Meanwhile, prolonged activation of PI3K/AKT and ERK signaling disrupts the regulation of cell growth and division, leading to the characteristic features of Noonan syndrome (OMIM# 163950) that is caused by germline variation in KRAS genes (PTPN11, SOS1, RAF1, LZTR1, etc.)." (PMID 31752936, 2019). "Supporting the fact that V14 is an important hub in the KRAS hydrophobic interaction network, a mutation in this position, V14I, is found to be one of the responsible mutations for the Noonan syndrome and may also predispose tumor development." (PMID 30199525, 2018). "Noonan syndrome (NS) is a RASopathy most frequently associated with mutations in HRAS, NRAS, KRAS, and RRAS2." (PMID 41517739, 2026). "Rare pathogenic variants in the PTPN11, KRAS, SOS1 and RAF1 genes are the main molecular causes of Noonan syndrome (NS)." (PMID 40041314, 2025). "Two of these participants have Noonan syndrome with pathogenic variants in PTPN11 (n = 1) and KRAS (n = 1)." (PMID 37774117, 2024). "Two of these individuals have Noonan syndrome (PTPN11 and KRAS variants) and three individuals have Cardiofaciocutaneous syndrome (KRAS variants)." (PMID 37774117, 2024). "The following diseases were found in two or more cases: Joubert syndrome (IFT74/CPLANE1, n = 2) and Noonan syndrome (PTPN11/KRAS, n = 3)." (PMID 37895220, 2023). "Mutations associated with Noonan syndrome alone include CBL, BRAF, KRAS, LZTR1, MAP2K1 (MEK1), NRAS, PTPN11, RAF1, RIT1, SOS1 and SOS2." (PMID 38550930, 2023). "Over the years, several other genes involved in Noonan syndrome (KRAS, SOS1, RAF1, MAP2K1, BRAF, NRAS, RIT1, and LZTR1) have been identified, acting at different levels of the RAS-mitogen-activated protein kinase pathway." (PMID 38254922, 2023). "The KRAS gene, along with LZTR1 and SOS2, is one of the three Noonan syndrome-causing genes in this group." (PMID 35813072, 2022). "RAS paralogs (HRAS, NRAS and KRAS) are of major interest in biology because they are involved in developmental disorders (e.g., Costello and Noonan syndromes) and in a broad variety of human neoplasia." (PMID 33187149, 2020).
Noonan syndrome (continued). "Germline mutations in KRAS have been identified in patients with cardiofaciocutaneous (CFC) syndrome, Noonan syndrome and Costello syndrome." (PMID 26521233, 2015). "For example, in Noonan syndrome, NRAS or KRAS can be mutated at various positions along their coding sequences in the germline." (PMID 26274561, 2015). "This corroborates the finding that patient’s with Costello Syndrome (HRAS germline mutation), Noonan Syndrome (NRAS, KRAS, PTPN11 germline mutations) and Neurofibromatosis (NF1 germline mutation) all have increased risk of developing fusion-negative RMS." (PMID 25768946, 2015). "In contrast, until now, an association between KRAS and short stature in Noonan syndrome has not been reported." (PMID 40332000, 2025). "In addition to the PTPN11 mutations in the RAS‐MAPK signaling pathway, including KRAS, SOS1, RAF1, SHOC2, NRAS, BRAF and CBL, can also cause Noonan syndrome." (PMID 37525886, 2023). "An analysis of neonatal blood spots has identified such somatic RAS pathway mutations (most commonly in PTPN11, NRAS and KRAS) in 38% of children (n = 34) without Noonan Syndrome but presenting with JMML at a median age of 1.5 years." (PMID 35409034, 2022). "Somatic KRAS mutations are often detected in patients with solid and non-solid tumors, whereas germline KRAS mutations are implicated in patients with the Noonan syndrome, cardio-facio-cutaneous (CFC) syndrome and Costello syndrome." (PMID 30012129, 2018). "These heart defects had not been seen in a syndromic context with her retinal changes before genetic testing, and sequencing of PTPN11 and KRAS for suspected Noonan syndrome had revealed no mutation." (PMID 29555955, 2018). "In addition, we verified by exomeanalysis that the patient did not have any pathogenic variants in the genes associatedwith Noonan Syndrome and other rasopathies (PTPN11,SHOC2, KRAS, CBL,SOS1, RAF1, HRAS,NRAS, RASA1, SPRED1,BRAF, MAP2K1, MAP2K2, RIT1 andRRAS)." (PMID 27561113, 2016). "In the absence of SH3BP2 mutation in an individual considered to have Cherubism, genetic screening for mutations in genes implicated in Noonan syndrome (PTPN11, SOS1, RAF1, KRAS, NRAS, and BRAF), NF1, and craniofacial cutaneous syndrome (BRAF, MAP2K1) should be undertaken." (PMID 25409853, 2014). "Interestingly, the remaining genes found to result in the clinical features of Noonan syndrome also involve the Ras-MAP kinase signaling system, including mutations in KRAS, SOS1 and RAF1." (PMID 22011734, 2011). "Furthermore, LZTR1 loss-of-function mutations linked to Noonan syndrome and schwannomatosis underscore its critical role in maintaining RAS signaling homeostasis, providing a molecular rationale for therapeutic strategies targeting KRAS degradation." (PMID 40427667, 2025). "Noonan syndrome is a cluster of monogenic conditions involving several genes in the RAS-MAPK pathway (PTPN11, SOS1, SHOC2, MAP2K1/2 and KRAS in the included paper)." (PMID 36729042, 2023). "De novo heterozygous missense variation at Val14 of KRAS, the homologous equivalent of Val25 in RALA, was previously reported in four unrelated individuals with Noonan syndrome." (PMID 30500825, 2018). "Eleven patients with Noonan syndrome with lymphatic abnormalities (5 female, 6 male; 7 infants, 4 adults; mean age 10.8 ± 16.4 years) were identified (PTPN11 n = 5/11 [45.5%], RIT1 n = 5/11 [45.5%], KRAS n = 1/11 [9%])." (PMID 35778409, 2022). "While the majority of those with Noonan Syndrome carry germline mutations in RAS pathway genes (e.g., PTPN11, KRAS, NRAS, SOS-1, RAF1, BRAF), not all develop JMML." (PMID 35409034, 2022).
Noonan syndrome (continued). "This contrasts with children without Noonan Syndrome bearing somatic RAS mutations in PTPN11, NRAS and KRAS, who account for a significant proportion of JMML cases." (PMID 35409034, 2022). "Since fibrous osseous dysplasia has been described in cherubism and sporadically in Noonan syndrome, sequencing of exon 9 of the SH3BP2 or KRAS, BRAF and PTPN11 genes was performed, but no pathogenic variant was detected." (PMID 33685999, 2022).
cervical carcinoma (64 papers, 2011 to 2026). A carcinoma arising from either the exocervical squamous epithelium or the endocervical glandular epithelium. "In summary, KRAS mutation and subsequent overexpression are key factors enabling cervical cancer cells to acquire ferroptosis resistance." (PMID 41479924, 2025). "In radioresistant cervical cancer, Kirsten rat sarcoma viral oncogene homolog (KRAS)–driven cell migration has been linked to the activation of the cellular-Raf (c-Raf)/p38 MAPK pathway." (PMID 41211420, 2025). "Extending the earlier work on organoid culture establishment, recent efforts used whole-exome sequencing and transcriptome analyses to identify upregulated MYC expression and activating KRAS mutations in patient-derived cervical cancer organoids." (PMID 37173984, 2023). "In cervical cancer, the presence of KRAS mutations was an independent predictor of disease recurrence." (PMID 34778082, 2021). "Despite an intensive literature search, we were unable to identify uterine cervical cancer cell lines with simultaneous mutations in KRAS and SMAD4, supporting the idea that this mutation signature is rare among uterine cervical cancers." (PMID 30220971, 2018). "KRAS mutation appears to be a rare event in other squamous cell tumours, such as head and neck cancer and cervical cancer." (PMID 24642661, 2014). "Our findings with regard to DNMT3L methylation and KRAS mutation need to be investigated further as recently aberrant promoter hypomethylation of DNMT3L has been linked with cervical cancer tumorigenesis." (PMID 21347319, 2011). "Furthermore, the involvement of the miR-30c-5p targeting the METTL3/KRAS axis is crucial in driving the progression of cervical cancer, shedding light on the molecular mechanisms underlying cervical cancer growth and metastasis." (PMID 39155349, 2024). "Also, although miR-486-3p is a potential strategy to inhibit cervical cancer progression, KRAS mutation in CRC was associated with upregulation of miR-486-3p and downregulation of miR-378." (PMID 33997035, 2021). "Given that KRAS-mutant cervical cancer also shows reduced sensitivity to platinum/taxane-based chemotherapy, combining ferroptosis inducers with conventional chemotherapeutic agents offers a promising new approach to overcome this therapeutic resistance." (PMID 41479924, 2025). "A phase II clinical trial is currently underway to evaluate the efficacy of combining Trametinib and AKT inhibitor GSK21411795 for the treatment of recurrent cervical cancer with PIK3CA and KRAS mutation." (PMID 38356704, 2024). "Meanwhile, studies have demonstrated that miR-30c-5p promotes iron death of cervical cancer cells by inhibiting the METTL3/KRAS axis, consequently inhibiting tumor growth, migration, and metastasis." (PMID 39155349, 2024). "For example, a unique set of endometrial-like cervical cancers, comprised predominantly of HPV-negative tumors, were reported with relatively high frequencies of KRAS, ARID1A, and PTEN mutations." (PMID 38067297, 2023). "Inhibition of oncogenic KRAS signaling by application of the MEK inhibitor trametinib led to apoptosis of the cervical cancer organoids, thus showing the potential of such approaches to direct clinical decisions." (PMID 37173984, 2023). "The in vitro results above showed that the antiferroptotic effect promoted KRAS-mediated tumorigenesis in cervical cancer cells, and our previous RNA-seq data also indicated that a series of ferroptosis-related genes changed in the SIL to SCC transition." (PMID 35422066, 2022).